AGR2 (anterior gradient 2, protein disulphide isomerase family member)
Diseases named in the same sentence as AGR2 in open-access papers (continued):
Sharing a sentence is not in itself a finding about the gene and the disease.
pancreatitis (5 papers, 2010 to 2023). Inflammation of the pancreas. "The impact of AGR2 on EGFR presentation to the cell surface is essential for pancreatitis-associated tissue regeneration in mice." (PMID 33413231, 2021). "This study establishes an essential role for AGR2-induced EGFR signaling in pancreatitis-associated tissue regeneration." (PMID 27764193, 2016). "Thus, consistent with previous work, pancreatitis-associated AGR2 expression initiates EGFR cell signaling, activates YAP1, and induces AREG expression." (PMID 27764193, 2016). "The present study therefore establishes for the first time the induction of four molecules, AGR2, EGFR, YAP1, and AREG, each of which have been individually associated with tissue regeneration in other organs, but are now all activated during pancreatitis." (PMID 27764193, 2016). "Histology of 3-week old wild-type AGR2+/+ and AGR2-/-null mice with caerulein-induced pancreatitis exhibited edema and inflammatory infiltrates, but as expected to a significantly lesser degree than the 2-day caerulein injection protocol." (PMID 27764193, 2016). "AG1478-treated and AGR2-/-null mice with pancreatitis died whereas all wild-type controls recovered." (PMID 27764193, 2016). "As will be described in detail below, the following experiments were performed after only 1-day of 8 hourly caerulein injections because pancreatitis reduced the viability of mice that were AGR2-/-null mutants or pharmacologically manipulated." (PMID 27764193, 2016). "AG1478-treated AGR2+/- heterozygotes with pancreatitis also exhibited significantly reduced nuclear EGR1 compared to AG1478-untreated heterozygotes, but MKI67 was not significantly affected." (PMID 27764193, 2016). "AGR2+/- heterozygotes were therefore able to survive pancreatitis, but exhibited lower levels of EGFR signaling and cell proliferation, and higher levels of serum amylase than wild-type controls." (PMID 27764193, 2016). "As a biomarker of disease severity, serum amylase levels of the AGR2+/- heterozygotes were markedly higher than AGR2+/+ wild-type mice with pancreatitis." (PMID 27764193, 2016). "Despite the poor outcomes, the histology of AGR2-/- null mice with pancreatitis revealed lower levels of inflammatory infiltrate and edema than its wild-type counterpart." (PMID 27764193, 2016). "Pancreatitis-induced AGR2 expression enabled EGFR translocation to the plasma membrane, the initiation of cell signaling, and cell proliferation." (PMID 27764193, 2016). "AGR2-/-null mice with pancreatitis exhibited serum amylase levels greater than 4-fold higher than 3-week old AGR2+/+ wild-type mice, and were the highest amylase levels among all groups tested." (PMID 27764193, 2016). "All 3-week old wild-type AGR2+/+ mice (n = 5) recovered from the pancreatitis induced with 1-day of 8 caerulein injections." (PMID 27764193, 2016). "Protein immunoblots of pancreatic homogenates revealed pancreatitis induced AGR2 protein expression and EGFR phosphorylation." (PMID 27764193, 2016). "Consistent with previous studies, both AGR2+/+ wild-type and AGR2-/-null mice with pancreatitis showed a marked increase in nuclear SOX9 in acinar cells." (PMID 27764193, 2016). "AGR2 expression was induced by pancreatitis as detected by RT-qPCR and protein immunoblotting of pancreatic lysates." (PMID 27764193, 2016). "Six to 8-week old AGR2+/- heterozygous mice with pancreatitis induced by 1 day of 8 hourly injections displayed cell surface EGFR." (PMID 27764193, 2016). "Although EGFR signaling and cell proliferation, as represented by nuclear EGR1 and MKI67, were significantly induced in AGR2+/- mice with pancreatitis on Day 1, the levels were 65% and 75% lower, respectively, than wild-type AGR2+/+ mice." (PMID 27764193, 2016).
pancreatitis (continued). "Consistent with previous work in which AGR2 expression in non-transformed cells resulted in translocation of EGFR to the cell surface and cell signaling, the present study demonstrated that pancreatitis induced AGR2 expression also achieved similar results." (PMID 27764193, 2016). "The increased severity of pancreatitis in AGR2-/-null mice was reflected in the higher serum amylase levels and their early demise." (PMID 27764193, 2016). "YAP1 activation was also dependent on pancreatitis-induced AGR2 expression." (PMID 27764193, 2016). "The present study employed the caerulein-induced pancreatitis model to test the hypothesis that AGR2-induced EGFR signaling is necessary for pancreatic tissue regeneration in higher vertebrates." (PMID 27764193, 2016). "The use of histologic criteria, such as the degree of inflammation, to characterize experimental pancreatitis may be misleading in the AGR2-/- null mouse because EGFR signaling is required for the inflammatory response." (PMID 27764193, 2016). "Whether AGR2-induced EGFR signaling is essential for tissue regeneration in higher vertebrates was evaluated using a well-characterized murine model for pancreatitis." (PMID 27764193, 2016). "In addition, the Hippo signaling coactivator YAP1 was evaluated in the context of AGR2 expression during pancreatitis." (PMID 27764193, 2016). "Whether AGR2 expression also results in YAP1 activation in pancreatitis was explored." (PMID 27764193, 2016). "Considering that AGR2 was previously associated with tissue regeneration in several lower vertebrates and its importance in EGFR-mediated cell signaling, experiments were conducted to evaluate its role in the murine model of pancreatitis-associated tissue regeneration." (PMID 27764193, 2016). "The murine model that employed caerulein-induced pancreatitis demonstrated the AGR2-induced EGFR signaling, which is necessary for tissue regeneration and the outcome of pancreatitis." (PMID 37175601, 2023). "The impact of AGR2 expression and EGFR signaling on tissue regeneration was evaluated using the caerulein-induced pancreatitis mouse model." (PMID 27764193, 2016). "From this perspective, the model clearly demonstrated AGR2's importance for both EGFR signaling and cell proliferation in response to pancreatitis." (PMID 27764193, 2016). "The results indicate a gene dosage effect between AGR2 and EGFR signaling that affected pancreatitis outcomes." (PMID 27764193, 2016). "AGR2-induced EGFR signaling was essential for tissue regeneration and recovery from pancreatitis." (PMID 27764193, 2016). "AGR2 is not expressed in the normal pancreas, but is induced early in the course of pancreatitis, which results in EGFR delivery to the cell surface where signaling is initiated." (PMID 27764193, 2016). "In contrast to the AGR2-/-null mice, AGR2+/- heterozygous mice could tolerate two days of caerulein injections and recovered fully from the pancreatitis after 9 days when no further cell proliferation was detected in the acinar cells (data not shown)." (PMID 27764193, 2016). "AGR2-/-null mice, however, showed higher baseline AXIN2 expression, which was not induced with pancreatitis." (PMID 27764193, 2016). "The AGR2-/-null mouse exhibited constitutive expression of AXIN2, suggesting that Wnt signaling is active, but was not induced with pancreatitis." (PMID 27764193, 2016). "Consistent with the absence of AGR2 expression in AGR2-/-null mice, EGFR protein remained in the endoplasmic reticulum during caerulein-induced pancreatitis." (PMID 27764193, 2016). "The present study established that the normal pancreas does not express AGR2, and EGFR signaling is inactive unless pancreatitis is induced." (PMID 27764193, 2016). "EGFR inhibition with AG1478 in wild-type mice with pancreatitis still exhibited a significant increase in nuclear YAP1, which was absent in the AGR2-/-null mice." (PMID 27764193, 2016).
cervical cancer (4 papers, 2018 to 2022). A primary or metastatic malignant neoplasm involving the cervix. "In cervical cancer Caski cells, we observed the effect on cell proliferation and apoptosis by transfecting miR‐3647‐5p mimic (miR‐3647‐5p) with AGR2 overexpression." (PMID 31436390, 2019). "Consistent with previous studies, AGR2 expression was positively correlated with adenocarcinoma and poor prognosis in cervical cancer in this study." (PMID 30406031, 2018). "Taken together, these data support AGR2 involvement in cervical cancer tumorigenesis by promoting the proliferation of human cervical cancer cells." (PMID 30406031, 2018). "Moreover, AGR2 overexpression can attenuate the inhibitory effect of miR‐3647‐5p on the proliferation of cervical cancer cells and the promotion of apoptosis, suggesting that AGR2 plays an oncogenic role in cervical cancer." (PMID 31436390, 2019). "Therefore, we analyzed the transcriptome sequencing by bioinformatics, and found that compared to normal cervical tissues, the expression of AGR2 were significantly upregulated in cervical cancer tissues." (PMID 31436390, 2019). "So is the effect of miR‐3647‐5p on cervical cancer cells Caski cells related to AGR2?" (PMID 31436390, 2019). "Through bioinformatics analysis, we found that AGR2 is highly expressed in cervical cancer tissue." (PMID 31436390, 2019). "In addition, we also found that miR‐3647‐5p can inhibit the proliferation of cervical cancer cells and promote apoptosis by targeting AGR2." (PMID 31436390, 2019). "The correlation between AGR2 and cervical cancer is still unclear." (PMID 31436390, 2019). "However, the correlation between AGR2 and cervical cancer is unclear." (PMID 31436390, 2019). "The identified proteins (AGR2, BRD7, and POM121) were differentially expressed according to cell type, clinical prognostic factors, and resistance to radiation therapy in cervical cancer patients." (PMID 30406031, 2018). "In conclusion, AGR2 and BRD7 expression have prognostic significance in cervical cancer and provide opportunities for improved treatment options." (PMID 30406031, 2018). "Furthermore, we demonstrated for the first time that low expression of AGR2, high expression of BRD7 or POM121 combined with low expression of PAUF predict delayed recurrence in cervical cancer patients." (PMID 30406031, 2018).
cervical cancer (continued). "Furthermore, we demonstrated that AGR2, BRD7, and POM121 protein expression had prognostic value when combined with PAUF expression using an analysis of a large cohort of cervical cancer patients." (PMID 30406031, 2018). "In addition, the higher expression of AGR2 was negatively correlated with LVSI and the depth of invasion (p = 0.007 and p = 0.042, respectively), and POM121 expression was decreased (p = 0.001) in radiation-resistant cervical cancer." (PMID 30406031, 2018).
chronic pancreatitis (4 papers, 2010 to 2020). A chronic inflammatory process causing damage and fibrosis of the pancreatic parenchyma. "Immunohistochemical analysis of chronic pancreatitis (CP) and peritumoral areas in PDAC tissues showed that AGR2 was present in tubular complexes (TC) and early pancreatic intraepithelial neoplasia (PanINs)." (PMID 27941872, 2017).
endometrial carcinoma (4 papers, 2018 to 2025). A malignant tumor arising from the epithelium that lines the cavity of the uterine body. "Previous research indicated that knockdown of AGR2 in human RL952 endometrial carcinoma cells resulted in the downregulation of genes related to glycolysis and a decrease in lactate production, indicating an impairment of glycolysis." (PMID 40281598, 2025). "Moreover, in endometrial cancer with overexpressed AGR2, Ki67-positive rate was accordingly elevated, indicating the detrimental role of Ki67 in tumors." (PMID 34793477, 2021).
esophageal adenocarcinoma (4 papers, 2014 to 2022). A malignant tumor with glandular differentiation arising predominantly from Barrett mucosa in the lower third of the esophagus. "In esophageal adenocarcinoma, AGR2 expression also promotes tumor growth, cell migration, and cellular transformation." (PMID 36327302, 2022). "They demonstrated that the presence of diffuse AGR2 expression is highly sensitive to esophageal adenocarcinoma." (PMID 36327302, 2022). "AGR2 is universally overexpressed in the epithelium of Barrett’s esophagus and esophageal adenocarcinoma." (PMID 36327302, 2022). "AGR2 is an ER chaperone which functions as a proto-oncogene in breast, colon, and esophageal adenocarcinoma." (PMID 29267283, 2017). "AGR2 has been found to be expressed highly in diverse human cancers, including adenocarcinomas of the esophagus, lung, pancreas, ovary and prostate." (PMID 25367337, 2014). "Because AGR2 is not universally expressed in ESCC, a predictor is of greater importance in esophageal adenocarcinoma." (PMID 36327302, 2022).
meningioma (4 papers, 2017 to 2022). A generally slow growing tumor attached to the dura mater. "In meningioma tissues and primary cell lines, the AGR2 expression levels and the associated effects on the chemotherapeutic agents, cisplatin and etoposide were investigated using transcriptome microarray analysis and immunofluorescence staining." (PMID 31247903, 2019). "Indeed, AGR2 has previously been implicated as a novel stem cell biomarker overexpressed in a subset of aggressive primary meningioma cell lines." (PMID 33167358, 2020). "Importantly, our data shows a novel association of AGR2 in meningioma stem cells." (PMID 28736504, 2017). "The high expression of AGR2 has been previously associated with the expression of Nestin, CD133 and SOX2 in high-grade meningioma tissues." (PMID 36482387, 2022). "Data from a gene expression meta-analysis considered AGR2 as an important biomarker for disease progression in meningiomas." (PMID 31247903, 2019). "The results showed that aggressive meningioma tumors had a significantly higher AGR2 protein expression and that cells that express high levels of AGR2 were more resilient to chemotherapeutic treatment." (PMID 31247903, 2019). "In situ and in vitro analyses of meningioma tissue and cell lines showed a high expression of AGR2, particularly in aggressive tumors." (PMID 31247903, 2019). "In meningioma, the intracellular AGR2 expression was shown to co-localize with Bmi-1 and was regionally correlated with cancer stem cell markers Nestin, prominin 1 (CD133) and Sox2 in high-grade tumors." (PMID 31247903, 2019). "Whole transcriptome microarray analysis for six tumor samples identified two groups of meningiomas with differential stem cell related pathways and a number of novel stem cell related biomarkers, including AGR2." (PMID 28736504, 2017). "Among the top genes with concordant upregulated expression at the transcript and proteomic level in grade III vs. grade I meningiomas was AGR2, a metastatic oncogene coding for the disulfide isomerase endoplasmic reticulum protein, anterior gradient 2 homolog (AGR2)." (PMID 33167358, 2020). "The top clinically relevant deregulated cancer genes in AGR2 high meningiomas were presented." (PMID 31247903, 2019). "Hence, combined, these data suggest AGR2 may be a contributor to an aggressive meningioma phenotype and should be considered as a possible molecular marker or therapeutic target on the transcript or protein level." (PMID 33167358, 2020). "Notably, AGR2 is not expressed in normal brain tissues, and it was shown to be preferentially expressed in high grade meningiomas compared to low grade meningiomas." (PMID 36482387, 2022).
metastatic tumors (4 papers, 2010 to 2024). "In precancerous lesions, primary tumors and metastatic tumors, the expression of AGR2 is increased, which has aroused our interest." (PMID 37197416, 2023). "AGR2, as a promising biomarker, has aroused great interest because of its increased expression pattern in precancerous lesions, primary tumors and metastatic tumors, which is used to detect the most common cancers." (PMID 37197416, 2023). "However, comparison of AGR2 expression between the primary and metastatic tumors in general showed lower levels of AGR2 in the metastatic tumors with respect to the primary tumor site." (PMID 32570918, 2020). "In addition, circulating tumor cells from patients with advanced metastatic disease display elevated AGR2 gene expression suggesting that AGR2 may play a functional role in metastasis or may represent a useful biomarker of circulating tumor cells." (PMID 20525245, 2010).
prostate adenocarcinoma (4 papers, 2010 to 2022). "At the RNA and protein level, there was an increase in AGR2 expression in adenocarcinoma of the prostate compared to morphologically normal prostatic glandular epithelium." (PMID 21144054, 2010). "In prostate adenocarcinoma, AGR2 could enhance the antitumor effect of bevacizumab." (PMID 36327302, 2022).
thyroid cancer (4 papers, 2014 to 2024). "AGR2 immunostaining was unrelated to parameters of tumor aggressiveness in pancreatic, ovarian, and thyroidal cancer as well as papillary renal cell carcinoma although tumors with lower AGR2 expression often tended to exhibit more unfavorable tumor features." (PMID 39533806, 2024). "Both thyroid carcinomas showed increased levels of other key proteins with known carcinogenic roles such as tenascin and AGR2." (PMID 27025787, 2016). "Here, we demonstrated that AGR2 plays a key role in thyroid cancer cell survival, migration, invasion and protection from ER stress." (PMID 24976026, 2014). "AGR2 is a novel marker of PTC and plays a role in thyroid cancer cell survival, migration, invasion and protection from ER stress." (PMID 24976026, 2014).